SOX17 (SRY-box transcription factor 17)
Diseases named in the same sentence as SOX17 in open-access papers (continued):
Sharing a sentence is not in itself a finding about the gene and the disease.
tumor (continued). "On the other hand, SOX17 promotes tumor angiogenesis and destabilizes tumor vessels in Lewis lung cancer, resulting in tumor metastasis and resistance to cisplatin." (PMID 33791203, 2021). "Quantitative RT-PCR (RT-qPCR) revealed that genes representing mesodermal (T, Kdr), endodermal (Foxa2, Gata4/6, Sox17) and ectodermal (Fgf5, Sox11 for primitive ectoderm) differentiation were generally activated in tumor." (PMID 33468253, 2021). "A single missense mutation in a SOX17 gene can change the DNA-dependent heterodimer formation with Oct4, interfering with the WNT/β-catenin pathway and inhibiting tumor metastasis via Wnt signaling." (PMID 33152990, 2020). "As the quantity of circulating tumor DNA for detection is related to stage and tumor volume, we explored the diagnostic accuracy of the combination of best three genes (CDO1, SOX17, and HOXA7) according to tumor size." (PMID 32138766, 2020). "SOX17-HMG-box domain mutations decrease its interaction with the β-catenin gene promoter and inhibit tumor formation." (PMID 33152990, 2020). "Yamamoto and his colleagues observed concordant methylation levels of tumor-related SOX17 gene in gastric-juice derived exosomal and nuclear DNA, suggesting that methylated DNA is efficiently packaged in exosomes." (PMID 33297544, 2020). "We and others have previously reported the dysregulated tumor suppressive function of SOX17 [SRY (sex determining region of Y chromosome)-box 17] transcription factor in ESCC." (PMID 30777052, 2019). "Collectively, our study provides a novel insight into reactivation of tumor suppressive function via SOX17-mediated transcription as critical targets in overcoming resistance in ESCC." (PMID 30777052, 2019). "Overexpression of TRIM30 promoted tumor growth in nude mice, whereas overexpression of Sox17 inhibited tumor growth." (PMID 31823782, 2019). "We identified that the alteration frequency was highest (5%) in SOX17, which is involved in oncogenesis through tumour suppression, down-regulating MAML3 expression, modulating nuclear β-catenin and antagonizing Wnt signaling." (PMID 31879572, 2019). "Further, SOX17, a transcription factor important for embryonic development and cell fate determination, and the tumor suppressors SEPINB5 and PTRO were underexpressed with underlying reduced copy number." (PMID 31682594, 2019). "The SOX17 protein expression was scored as stained intensity × percentage of tumor regions of endoscopic samples." (PMID 30777052, 2019). "Next, SOX17 was found to suppress tumor formation by inhibiting cell proliferation in vivo and in vitro through tumor xenograft, cell growth and cell viability assays." (PMID 29970906, 2018). "In 4/6 patients that relapsed SOX17 gene promoter was found highly methylated in the primary tumour, in the corresponding CTC-fraction and in ctDNA." (PMID 29069768, 2017). "For example, aberrant DNA methylation of SOX17 has been identified not only in tumor tissue but also in plasma DNA, and SOX17 appears to be hypermethylated in luminal B tumors, but hypomethylated in basal-like tumors." (PMID 26884818, 2016). "In the in vivo study, SOX17 overexpression clearly restrained the tumor growth and increased the cisplatin toxicity and apoptosis of tumor cells." (PMID 27065754, 2016). "Our observations revealed that SOX17 overexpression correlated with reduced CyclinD1 and c-Myc levels, suggesting that SOX17 suppresses tumor growth through inhibition of β-catenin/TCF activity and the Wnt signaling pathway." (PMID 27738313, 2016). "Recent evidence has suggested that overexpression of the transcription factor SOX17 prevented apoptosis in tumor cell lines." (PMID 27065754, 2016).
tumor (continued). "In nude mice, SOX17 over-expression inhibited tumor growth, and co-inhibition or co-overexpression of SOX17 and MAML3 rescued this response." (PMID 27738313, 2016). "The data suggest that Sox17-mediated transcriptional regulatory patterns that are normally active during vascular development are reactivated in the context of tumor angiogenesis." (PMID 26630461, 2015). "We found that knockdown of SOX17 promoted cell proliferation and invasiveness in vitro, while reintroduction of miR-371-5p abolished the tumor promoting effects of SOX17 knockdown on CRC cells." (PMID 25868860, 2015). "In the mouse models of tumor growth and metastasis, SOX17 depleting cells were injected in subcutaneous site of nude mice or into tail vein to seed lung metastases, respectively." (PMID 25868860, 2015). "The most recent connection between human disease and SoxF genes comes from an analysis of Sox17 in tumor ECs." (PMID 26630461, 2015). "Based on these results it would be reasonable to conclude that SOX17 is sufficient to inhibit stem cell properties, tumor growth and metastasis in vivo by up-regulating miR-371-5p." (PMID 25868860, 2015). "For example, SOX7 and SOX17 have been suggested to suppress tumor growth through an interaction with β-catenin in various cancer types." (PMID 25427424, 2014). "Moreover, the activity of SOX17 has been studied in some tumor models and appears to function as a tumor suppressor." (PMID 41463503, 2025). "SOX17 is a transcription factor involved in the early stages of cancer, orchestrating an immune-evasive program that facilitates cancer initiation and progression while also regulating tumor angiogenesis." (PMID 40165955, 2025). "Furthermore, in addition to antagonizing the pro-tumorigenic Wnt/β-catenin signaling pathway, SOX17 functions as a tumor suppressor for several types of cancer in other endoderm-derived organs." (PMID 39745200, 2025). "Importantly, SOX17 has been identified as a key regulator of cholangiocyte differentiation and acts as a tumor suppressor in in vitro CCA models." (PMID 40980689, 2025). "We thus speculate that SOX17 expression may be related to HEV generation in tumor‐penetrating vessels." (PMID 39385307, 2024). "Overall, these studies indicate that SOX17 is not only crucial for immune evasion but also significantly impacts the tumor microenvironment by promoting angiogenesis and altering the immune landscape, making it a potential target for therapeutic intervention in cancer treatment." (PMID 38981872, 2024). "SOX17‐mediated CD8+ T‐cell‐rich tumor microenvironment might attract interest in improving the effect of cancer immunotherapy." (PMID 39385307, 2024). "Combined with the present findings of SOX17 immunoreactivity in TECs in 19 of 83 LUAD cases, we reasonably speculate SOX17's role in tumor angiogenesis in various human cancers." (PMID 39385307, 2024). "In tumor development and repression, SOX17 has conflicting roles." (PMID 38136277, 2023). "This revealed that MECOM, PAX8, SOX17 and WT1 are lineage-enriched, super-enhancer associated master regulators whose cooperative DNA-binding patterns and target genes are re-wired during tumor development." (PMID 37090516, 2023). "Epigenetic alterations, like DNA methylation, in the promoter regions of tumor/metastasis suppressor genes, such as SOX17, BRMS1, and CST6 in EpCAM+ CTCs isolated from individuals with BC, are known to be correlated with enhanced tumor metastasis and poor prognosis." (PMID 35303879, 2022). "The SOX17 transcription factor has been known to have tumor suppressive function in ESCC." (PMID 36072972, 2022).
tumor (continued). "In addition, SOX17 overexpression was found to inhibit tumor growth and metastasis in an ESCC xenograft model." (PMID 36072972, 2022). "Previously, we discovered that the expression of SOX17, a tumor-suppressive transcriptional regulator with a high mobility group (HMG) box domain that interacts with SRY binding site in DNA, is significantly downregulated due to promoter hypermethylation in ESCC patients with poor prognosis." (PMID 36310172, 2022). "However, the silencing of VE-cadherin expression significantly inhibits Cyclin D1 expression and enhances SOX17 expression, which can inhibit tumor progression." (PMID 36072972, 2022). "On Cox regression model analysis, various factors, such as gender, age, tumor type, tumor location, tumor diameter, histological grade, lymph node metastasis, depth of invasion, pTNM stage, VM, SOX17 expression, Cyclin D1 expression, and VE-cadherin expression, were identified as prognostic factors." (PMID 36072972, 2022). "Notably, SOX17 was recognized as a tumor-suppressive transcription factor that negatively regulates DNA repair genes in ESCC." (PMID 36310172, 2022). "SOX17 was also detected in the tumor thrombus of CRPC suggesting that activated SOX17 may be associated with tumor metastasis." (PMID 33791203, 2021). "Notably, the promoter of the WNT–β-catenin pathway inhibitor SOX17 was hypermethylated in CCA tumour tissue compared with healthy tissue, correlating with a worse prognosis after tumour resection." (PMID 32606456, 2020). "Interestingly, while the combination of CDO1, SOX17, and HOXA7 showed the overall best performance in our patient cohort, the combination of CDO1, TAC1, and SOX17 had the best performance in the subgroup with tumor size less than 1.0 cm." (PMID 32138766, 2020). "IHC for MUC1 and SOX17 on both tumor and normal organoids has confirmed their glandular origin." (PMID 32552764, 2020). "In the present study, the gene panel CDO1, SOX17, and HOXA7 showed the best diagnostic accuracy in the subgroup with tumor size 2.1-3 cm and decreased in subgroups with smaller tumor size, especially when the tumor size was less than 1 cm." (PMID 32138766, 2020). "As expected, Sox17 overexpression counteracted the TRIM30-mediated tumor growth." (PMID 31823782, 2019). "Notably, promoter hypermethylation of SOX17 gene leading to silence of SOX17 protein can be found in tumor of ~ 50% ESCC patients analyzed." (PMID 30777052, 2019). "The use of DNA demethylation reagents may exert tumor inhibition or sensitization effects through up-regulation of SOX17, inducing potent cytotoxicity in ESCC cells and their resistant cells in multimodality treatments." (PMID 30777052, 2019). "The opposite pattern of expression of Sox7 and Sox17 and the involvement of Sox18 in tumor vascularization suggests that SoxF family members may have different functions in ECs dependent on the niche, insult, or type of vascular beds." (PMID 31073164, 2019). "Only one POLE-mutated tumor harbored a SOX17 mutation and this mutation was likely not mutational noise secondary to the POLE defect since it was not a TCT>TAT or TCG>TTG transition." (PMID 28978154, 2017). "Recent data suggest that SOX17 is an important regulator of tumour angiogenesis." (PMID 28577909, 2017). "Low/absent SOX17 staining was significantly associated with advanced stage, high tumor grade and reduced recurrence-free survival." (PMID 28978154, 2017). "We further evaluated whether there is any association between SOX17, CST6, and BRMS1 promoter methylation in CTC, ctDNA and corresponding primary tumours and the clinical outcome of patients." (PMID 29069768, 2017). "Several studies suggest that HOXA9 and SOX17 are involved in tumor progression." (PMID 29270240, 2017). "In this study, we evaluated SOX17 expression in EC patient tumor samples and cell lines." (PMID 27738313, 2016). "Tumor weights and sizes from SOX17-overexpressing cells were reduced compared to controls." (PMID 27738313, 2016).
tumor (continued). "Our results suggest that decreasing SOX17 levels may promote EC development and progression, and that by downregulating MAML3 expression and Wnt signaling, SOX17 acts as a tumor suppressor that may improve outcome in patients with EC." (PMID 27738313, 2016). "The tumor sizes of the SOX17 group were significantly smaller than those of the control group." (PMID 27065754, 2016). "Our observations suggest that decreased SOX17 levels may promote EC development and progression, and that SOX17 is a tumor suppressor in EC." (PMID 27738313, 2016). "Our results indicated that SOX17 was an important tumor suppressor in EC." (PMID 27738313, 2016). "TUNEL assays on the tumor samples confirmed the hypothesis that the inhibition of tumor growth in the SOX17 group was due to increased cell apoptosis." (PMID 27065754, 2016). "In addition, tumor growth curves indicated that after 10 days treatment, the tumors of the SOX17 group were smaller than those of the control." (PMID 27065754, 2016). "The SOX17 promoter was methylated in 86.0 % of tumor tissues." (PMID 26453190, 2015). "However, SOX17 inhibits canonical Wnt/β-catenin signaling and suppresses tumor growth in papillary thyroid carcinoma." (PMID 25427424, 2014). "Similarly, in one-third of our cases we observed amplification of this entire arm, while putative tumor suppressor genes, such as SOX17 and PENK, within this amplified chromosomal arm are methylated." (PMID 20300172, 2010). "Particularly in NSCLC, SOX proteins exhibit dual regulatory functions: Certain members (SOX2) may promote chemotherapy resistance by maintaining cancer stem cell properties, whereas others (SOX17) serve as tumor suppressors by inhibiting oncogenic signaling pathways." (PMID 41268614, 2026). "These oncogenic features of SOX17 and SOX18 are supported by their significant co-expression with endothelial and inflammatory mediators such as VCAM1 and STAT3, both of which are known to drive tumor-associated angiogenesis, immune evasion, and metastatic potential." (PMID 41373817, 2025). "Similarly, the role of SOX17 as a promotor of tumor angiogenesis has been described in mice." (PMID 39516198, 2024). "In addition, MALAT1 expression was adversely correlated to SOX17 expression in tumor tissues." (PMID 35614065, 2022). "In addition, SOX17 inhibits tumor growth and metastasis in ESCC xenograft animal model." (PMID 30777052, 2019). "Moreover, TRIM30/Sox17 axis also regulated tumor growth in nude mice." (PMID 31823782, 2019). "Knocking out PGC specification inducers (ACVR1, SMAD5, PRDM1, or SOX17) or fate-maintaining genes (NANOG or DDX4) suppressed both SPLC and tumor initiation." (PMID 42291258, 2026). "SOX30, in contrast to SOX17 and SOX18, exhibited suppressed expression at both mRNA and protein levels across tumor regions." (PMID 41373817, 2025). "In contrast, SOX17 and SOX18 exhibited pronounced nuclear and endothelial expressions in tumor tissues, with SOX17 particularly enriched in LUAD and SOX18 in both LUAD and LSCC." (PMID 41373817, 2025). "SOX17, a member of the SRY-box family, is essential for endodermal lineage commitment and functions as a tumor suppressor by repressing Wnt/β-catenin signaling." (PMID 41012596, 2025). "However, by upregulating VEGFR2 and improving the recruitment of myeloid-derived suppressor cells, which promotes vascular remodeling and reduces the production of IFN-γ and Th2 cytokines, SOX17 may potentially boost tumor angiogenesis and blood vessel instability." (PMID 38136277, 2023). "While SOX18 has been found to be overexpressed in tumours, SOX7 and SOX17 have been reported to be downregulated." (PMID 37511076, 2023). "Collectively, our data highlights that tumor-specific epigenetic remodeling is tightly related to MECOM, PAX8, SOX17 and WT1 activity and these transcription factors are targetable in a tumor-specific manner through transcriptional inhibitors." (PMID 37090516, 2023).
tumor (continued). "CTNNB1 binds directly various transcription factors, which are important for tumor progression including JUN, FOSL1, SRY box transcription factor 17 (SOX17), TCF3, TCF4, and TCF7." (PMID 36457029, 2022). "In particular, SOX17low/NRF2high nuclear level significantly correlated with poor CCRT response and poor survival, indicating that the dysregulation of SOX17/NRF2 axis played a pivotal role in CCRT resistance and tumor progression." (PMID 36310172, 2022). "In the present study, a significantly lower SOX17 expression was found in ESCC compared to the normal esophageal epithelium, confirming the tumor suppressive function of SOX17." (PMID 36072972, 2022). "The expression of SOX17 and miR-199a was downregulated and that of HIF1α and MALAT1 was upregulated in tumor tissues of mice in the KYSE150R + oe-NC group." (PMID 35614065, 2022). "SOX7, SOX17, and SOX18 belong to the SOXF family and are functionally redundant; moreover, SOX7 deletion in endothelial cells reduces tumor angiogenesis and promotes tumor vascular normalization." (PMID 34728626, 2021). "SOX17 (SRY-box containing gene 17) is homologous to the sex-determining gene SRY and a tumor suppressor in various cancers." (PMID 33791203, 2021). "To further explore the molecular mechanisms by which Sox17 exerts its tumor-inductive effects on PTC cells, we used immunoprecipitation coupled to mass spectrometry (IP-MS) to identify binding partners for Sox17." (PMID 31823782, 2019). "Meanwhile the expression of markers of poor prognosis (Muc1, CD146, and SOX17) and good prognosis (VDR) in the tissue of patient’s tumor tissue were consistent with corresponding cell lines." (PMID 31359275, 2019). "Nonetheless, we decided to focus on 4 TSGs (TFPI2, SOX17, GATA4, and FBN2) because we later confirmed that these genes had a cancer-specific methylation pattern in primary OSCC tumor samples." (PMID 31405379, 2019). "In contrast, SOX17 knockdown induced the Ki67 staining and IRS of tumor tissues weaker and lower, respectively, (6.67 ± 2.73 vs. 2.33 ± 0.82, p < 0.01, 1.80 ± 1.48 vs. 6.00 ± 3.58, p < 0.05)." (PMID 29970906, 2018). "For example, the gene SOX17, which was predicted to be regulated by four miRNAs in the subnetwork of KIRC, was considered an important tumor suppressor with aberrant methylation for the cancers." (PMID 28831388, 2017). "Our investigations revealed that SOX17 was inversely correlated with MAML3 expression in EC cell lines and tumor tissues." (PMID 27738313, 2016). "Analyses on 27 primary tumours confirmed the expression of some pluripotency genes (for example, OCT4 and KLF4) and endodermal stem cell traits (for example, SOX17 and PDX1) paralleling what was observed with the transplantable tumour line." (PMID 26437858, 2015). "In-silico analysis showed that several genes (CASZ1, IL1RAPL1, SOX17, N4BP1 and ARHGDIA) suggested to have tumor suppressive functions were target genes of miR-151." (PMID 22928040, 2012). "Next, we performed another comparative analysis of SOX17 protein expressions in different cancer versus adjacent normal tissues with the data available in The Clinical Proteomic Tumor Analysis Consortium (CPTAC) database." (PMID 41271627, 2025). "In contrast, SOX17 is upregulated in tumor regions—particularly in LUAD—supporting its emerging role as an oncogenic factor in NSCLC, potentially contributing to stem-like phenotypes and tumor identity." (PMID 41373817, 2025). "Analyzing the methylation of circulating tumor DNA (ctDNA), such as dynamic monitoring of SOX17 and TAC1, correlates with tumor burden and provides a non-invasive tracking option." (PMID 40725119, 2025).